RNU4-7P (RNA, U4 small nuclear 7, pseudogene)
Synonyms: U4; U4/7; formerly RNU4P1
Gene: Small nuclear RNA gene on chromosome 6 (150,326,623 to 150,326,763, reverse strand). Ensembl gene ENSG00000201628.
Homologues: Orthologues: chimpanzee U4 (97% identical). Paralogues in human: RNU4-13P (89% identical), RNU4-68P (89% identical), RNU4-67P (88% identical), RNU4-58P (86% identical), RNU4-8P (86% identical), RNU4-31P (84% identical), RNU4-44P (84% identical), RNU4-76P (84% identical), RNU4-92P (84% identical), RNU4-16P (84% identical), RNU4-42P (84% identical), RNU4-23P (83% identical), and 80 more.